BIRC3 (baculoviral IAP repeat containing 3)
Diseases named in the same sentence as BIRC3 in open-access papers (continued):
Sharing a sentence is not in itself a finding about the gene and the disease.
cancer (continued). "The cancer pathway finder PCR array revealed 9 genes, including ACSL4, BIRC3,CA9, CCL2, FLT1, FOXC2, G6PD, IGFBP3 and SNAI2, with significantly altered expression in the siRNA-treated MCF-7 cells." (PMID 27478411, 2016). "All these genes have already been associated with hypermutated regions in BCLs (BCL2, BCL6, BCL7A, BIRC3, CIITA and ST6GAL1) or listed in the Cancer Gene Census (BCL2, BCL6, BCL7A, BIRC3, CIITA, IGLL5 – in the IGL@ locus – and LPP)." (PMID 25903198, 2015). "The over-expression of IPS-1 downregulated the anti-apoptotic genes such as BCL2, BIRC3 and PRKCE, known to promote survival in different types of cancer." (PMID 25950488, 2015). "Staining for cIAP-2/BIRC3 was increased in the severe dysplasia/CIS category and in carcinomas compared to less advanced pathology grades." (PMID 16332260, 2005). "• Exertion of anticancer effects through 3 major pathways: apoptosis (BIRC3, BIRC5, caspase-8, caspase-9, and PARP1), transcriptional dysregulation in cancer (CDKN1A, CDKN1B, MMP9, MYC, JUN, and RELA), and cancer progression (caspase-3, CCND1, CTNNB1, VEGFA, and Wnt-1)." (PMID 39181121, 2025). "BIRC3 is highly expressed in PDAC and may contribute to cancer progression by modulating cell survival and death." (PMID 38254861, 2024). "The three clusters generated contained genes or proteins involved in apoptosis (BIRC3, BIRC5, PARP1, CASP8, and CASP9), transcriptional dysregulation in cancer (CDKN1B, RELA, CDKN1A, MYC, JUN, and MMP9), and cancer progression (CCND1, CASP3, CTNNB1, WNT1, and VEGFA) pathways." (PMID 34836311, 2021). "BIRC3 and MMP3 promote cancer cell survival and metastasis, respectively." (PMID 34172737, 2021). "Many evidences point to the pro-survival and antiapoptotic role of BIRC3 in cancer cells, however, not all the data are consistent and the resulting picture is heterogeneous." (PMID 33413657, 2021). "In addition, we obtained drug screen data from the “Genomics of Drug Sensitivity in Cancer” database for two TNF pathway compounds that inhibit TRAF2 binding partners, BIRC2/BIRC3 (IAP-5620) and BIRC2 (AZD5582)." (PMID 33508232, 2021). "There is substantial evidence pointing to the pro-survival and anti-apoptotic roles of BIRC3 in cancer cells; however, not all data are consistent." (PMID 34925455, 2021). "The concept arising from the recent literature is that the biological meaning of BIRC3 disregulation in cancer cells is not entirely predictable." (PMID 33413657, 2021). "For example, BIRC2 was clustered with BIRC3, XIAP and BIRC6 in more than 50% of the cancers." (PMID 31964418, 2020). "Hence, gain of the genes in apoptosis, including the anti-apoptosis genes BIRC2, BIRC3, and ATF5, can help carcinoma cells to evade apoptosis." (PMID 19911042, 2009). "Higher BIRC3 expression in OAC compared to OSCC, however, could suggest that BIRC3 contributes to the divergence in NAT response between the two histological subtypes and thus presents an avenue to elucidate molecular differences between the two cancers." (PMID 35205743, 2022). "Most genes from the “Pathways in cancer” (FLT3, IGF1R, DAPK2, PLD1 and MMP9) are inhibited due to the action of BE resulting in an anti-proliferative and pro-apoptotic action of the combined therapy, with the notable exception of the up-regulation of the apoptosis inhibitor BIRC3." (PMID 28359318, 2017). "Cancer and reproductive disease add prominent non-MHC signals at TERT and CLPTM1L alongside pan-category genes such as MIS18BP1 and BIRC3." (PMID 41166152, 2026). "We found the selective upregulation of TRAIL and downregulation of BCL2, BIRC3 and PRKCE in the MDAMB-231 cancer cells but not in the MCF10A cells." (PMID 25950488, 2015).
tumor (173 papers, 2008 to 2026). "The literature reports that Birc3 expression is associated with tumor prognosis, inflammatory response and immune disorders." (PMID 37753085, 2023). "BIRC3 is a hallmark of tumor-infiltrating NK cells, and upregulation of BIRC3 can inhibit NK cell activity." (PMID 35757748, 2022). "The analysis of the experimental evidences point to an apparent paradox of this cIAP, since in many instances BIRC3 plays a role of tumor suppressor, its deficiency being associated to poor prognosis and insurgence of therapy resistance (please)." (PMID 33413657, 2021). "Several were anti-angiogenic (Agtrap, Gem, Wdfy1) or anti-apoptotic (Birc3, Mnda), as demonstrated by their association with tumour metastasis." (PMID 29447208, 2018). "Meanwhile, BIRC3 was negatively correlated with tumor purity (Rho = − 0.43, p = 2.85 × 10− 20) and positively correlated with dendritic cell infiltration (Rho = − 0.475, p = 6.47 × 10− 25), suggesting that BIRC3 is associated with GBM TME infiltration." (PMID 40616096, 2025). "Notably, primary CLL samples derived from patients carrying BIRC3 mutations (n = 3) or NOTCH1 mutations (n = 1) in their CLL tumor cells were particularly sensitive to NIK inhibition." (PMID 35326640, 2022). "A previous study suggested that BIRC3 might play a role of tumor suppressor, because its deficiency was associated with poor prognosis of the patients, which is consistent with our data." (PMID 34692492, 2021). "Since BIRC2 and BIRC3 are adjacent, paralogous genes on human chromosome 11, it is not surprising that overexpression of cIAP2 has also been associated with the progression of the same tumor types and with treatment resistance." (PMID 29167558, 2017). "When these two observations are taken together, the data imply that the BIRC3 mutation may be present in a heterozygous state within the neoplasm (i.e., a tumor burden of approximately 10% with a heterozygous mutation would be expected to generate an allelic burden of approximately 5%)." (PMID 27993143, 2016). "Spatial transcriptomic analysis further identified region-specific expression patterns and spatially restricted tumor niches, including the regional establishment of TXNIP and BIRC3 as genes associated with metabolic stress and inflammatory survival pathways." (PMID 41972735, 2026). "In C1-GBM, key tumor driver genes included BIRC3 (Baculoviral IAP Repeat Containing 3), MET (MET Proto-Oncogene, Receptor Tyrosine Kinase), COL1A1 (Collagen Type I Alpha 1 Chain), CR1 (Complement C3b/C4b Receptor 1), and IL7R (Interleukin 7 Receptor)." (PMID 41614933, 2026). "Predictably, pharmacologic targeting of BIRC2 and BIRC3 will not only induce GBM tumor apoptosis but should also impact the TME as a whole." (PMID 40616096, 2025). "BIRC3 protein levels are elevated in tumor tissue and increase as the tumor progresses through various stages." (PMID 42164555, 2025). "The proportion of tumour nuclei exhibiting a spindle shape is significantly higher (P < 0.05) in the group of patients with altered BIRC3 in the external validation cohort across all survival endpoints." (PMID 40997749, 2025). "Overall tumor burden in the bone marrow remained high (> 40–50%) during the course of disease despite treatment as was allelic burden of BIRC3 and the patient finally succumbed to the disease." (PMID 37951851, 2024). "BIRC3/cIAP2 was abnormally elevated in the majority of human malignancies and promoted tumor progression by activating the NF-κB pathway." (PMID 38443362, 2024). "Currently, small molecule inhibitors or antibodies targeting BIRC3 are being developed as potential treatments to disrupt its E3 ubiquitin ligase activity and induce tumor cell apoptosis." (PMID 39301019, 2024).
tumor (continued). "Among them, ANXA1 and FKBP11 were highly expressed in tumor tissues compared to normal tissues, whereas BIRC3 and TNIP3 were lowly expressed in tumor tissues." (PMID 37047025, 2023). "Remarkably, we noted a higher proportion of epithelial cells (malignant tumor cells) and myeloid cells in patients exhibiting elevated BIRC3 expression, particularly evident in patient samples GSM4735375, GSM4735370, and GSM4630028." (PMID 38130918, 2023). "In comparison to normal tissue samples, the expression of BIRC3 is significantly elevated in the tumor." (PMID 38130918, 2023). "The subpopulation of cells with high expression of BIRC3 was involved in tumor suppressive regulatory role, while IRF7 recruited activated inflammatory cells producing interferons." (PMID 37533434, 2023). "The results showed that the transcriptional expression levels of NDRG1 (P < 0.001), ERRFI1 (P < 0.001), IRS2 (P < 0.001), IGFBP4 (P < 0.01), and BIRC3 (P < 0.01) were significantly decreased in tumor tissues, while SOCS1 (P < 0.05) expression was increased." (PMID 35859293, 2022). "Collectively, the data summarized above point to a tumor suppressive function of BIRC3, likely through the cooperation with other mediators." (PMID 33413657, 2021). "The expression of BIRC3 was found to correlate with that of HIF-1α in a hypoxic tumor region, and it was shown that BIRC3 is a key molecule mediating the survival adaptation in hypoxia-driven mesenchymal GBM habitats." (PMID 33762019, 2021). "BIRC3 is a downstream target regulated by this inhibitor and its expression anti-correlates with IBTKα-silencing, supporting its role as a tumor suppressor." (PMID 33413657, 2021). "In vivo silencing of BIRC3 suppressed tumor initiation and progression in GBM orthotopic intracranial xenografts." (PMID 35008722, 2021). "Some conflicting experimental data reporting either the oncogenic or the tumor suppressor role in the same type of malignancy strengthen the context-dependent and bi-faceted role of BIRC3." (PMID 33413657, 2021). "The strategy of preventing tumor initiation through depletion of BIRC3 is of clinical importance and addresses a major reason for treatment failures in GBM." (PMID 35008722, 2021). "BIRC3 overexpression accelerated tumor progression and significantly decreased survival (p < 0.023), while BIRC3 knockout significantly increased survival (p = 0.00008)." (PMID 35008722, 2021). "A similar expression pattern was observed between CD63 and BIRC3 (scLink’s correlation = 0.58, adjustedP = 0 in the tumor sample)." (PMID 34252628, 2021). "Lastly, we demonstrate that depletion of BIRC3 significantly suppressed tumor initiation and progression in GBM intracranial xenografts." (PMID 35008722, 2021). "The MRI results indicated that BIRC3 expression significantly facilitated GBM tumor initiation and progression, whereas BIRC3 knockout significantly inhibited tumor initiation and progression." (PMID 35008722, 2021). "Further evidences pointing to the tumor-suppressor role of BIRC3 in CLL arise from the characterization of IBTKα in CLL primary samples." (PMID 33413657, 2021). "Correspondingly, an immunostaining analysis of xenografted tumor tissues revealed that BIRC3 expression was also decreased in the HCP5 knockdown group." (PMID 31215169, 2019). "Three of these genes, apoptosis inhibitors BID, BIRC2 and BIRC3 were found in the differential expression analyses, being overexpressed in CTNNB1-mutated tumours." (PMID 31000732, 2019). "BNIP3 and BIRC3, the other two up-regulated genes by IBTKα RNA interference, are tumour suppressors." (PMID 29317636, 2018). "To assess BIRC3 protein expression in tumor cell niche versus vascular niche, we performed immunohistochemistry (IHC) analyses of a TMA comprised of patient-derived GBM biopsy samples as well as normal brain controls." (PMID 28839258, 2017). "Further, the combination of PDGFB and BIRC3 resulted in a significant decrease in tumor-free survival compared to controls." (PMID 27074575, 2017).
tumor (continued). "Nonetheless, BIRC3 protein expression appeared to be a robust habitat marker in GBM with a predilection towards the tumor cell niche compared to the vascular niche." (PMID 28839258, 2017). "Further, there was a relatively higher expression of BIRC3 in the tumor cell niche compared to the vascular niche suggesting that the tumor cells are largely responsible for BIRC3 expression." (PMID 28839258, 2017). "We were therefore interested in characterizing regional expression of BIRC3 protein in GBM using patient GBM tissue microarray with respect to tumor cell niche as well as vascular niche." (PMID 28839258, 2017). "Further, BIRC3 protein was highly expressed in the tumor cell niches compared to the perivascular niche across multiple regions in GBM patient tissue microarrays." (PMID 28839258, 2017). "Tumor hypoxia was found to mechanistically induce BIRC3 expression through HIF1-alpha signaling in GBM cells." (PMID 28839258, 2017). "In an effort to ascertain if our in vitro data on BIRC3 phenotype had any in vivo relevance, we established subcutaneous xenograft tumor models of both control U251 and BIRC3 over-expression U251 HG cells." (PMID 26888114, 2016). "The genomic instability of the miR-34a-high tumor cell line was reflected in high-copy amplicons coding for the oncogenes Yap1, Birc2, Birc3, Dcun1d5 (all on 9A1) or the leptin receptor (4C6)." (PMID 26871287, 2016). "We found that c-IAP1 (Birc2), XIAP (Birc4), Survivin (Birc5) and Livin (Birc7) were overexpressed in ESCC tissues, while NAIP (Birc1) and c-IAP2 (Birc3) were comparable between tumor tissues and adjacent non-tumor tissues." (PMID 25216531, 2014). "BIRC3 was detected in 50% of tumours, and APOL1 expression in 64%." (PMID 38254861, 2024). "Besides, we further analyzed the correlation between BIRC3 and tumor microenvironment score, and the results indicated that ESTIMATEScore, StromalScore, and ImmuneScore were significantly highly expressed in the high BIRC3 group." (PMID 38130918, 2023). "Besides, in mast cells, two NPA genes HSP90AA1 and HSP90AB1 were up-regulated in tumor tissues, whereas BIRC3 was down-regulated." (PMID 38149248, 2023). "Cells with reduced BIRC3 formed significantly fewer tumor nodules in the lungs." (PMID 37391410, 2023). "Meanwhile, BIRC3 may participate in the construction of an immunosuppressive tumor microenvironment, which may be a potential therapeutic target of ccRCC." (PMID 38130918, 2023). "Our research showed that BIRC3 is an important tumour-promoting gene in ccRCC." (PMID 38130918, 2023). "BIRC3 was a member of the anti-apoptotic protein family, which may promote carcinogenesis by inhibiting cell apoptosis and promote tumor metastasis and progression through necroptosis involving multiple pathways." (PMID 38130918, 2023). "Our results corroborate the findings that BIRC3 functions as a tumor suppressor." (PMID 36685836, 2022). "Importantly, tumor samples from a subset of poor prognosis CLL patients, with mutations in a gene called BIRC3, showed elevated p52 expression and were particularly sensitive to NIK inhibition." (PMID 35326640, 2022). "The tumor sphere formation assay results revealed that silencing BMP4 in BIRC3 knockout U251 cells significantly induced tumor sphere formation and rescued the loss of stemness which was previously induced by BIRC3 knockout (p < 0.05)." (PMID 35008722, 2021). "At this point, scientists could face a paradox and, given the great potential of Smac-mimetics, should clarify the role of BIRC3 in the tumor cell." (PMID 33413657, 2021). "Taken together, these data suggest that BIRC3 could impact on GBM tumor initiation, stemness and progression." (PMID 35008722, 2021). "Furthermore, TRAF2, BIRC3 and MAP3K14 were recurrently mutated in approximately 17% of a cohort of 165 MCL tumor tissues investigated by genomic profiling." (PMID 33413657, 2021).
tumor (continued). "We demonstrated in orthotopic intracranial xenografts that high BIRC3 expression could significantly promote tumor initiation and propagation and moreover BIRC3 depletion could enhance survival though suppressing of tumor initiation and growth." (PMID 35008722, 2021). "Lastly, we evaluated the impact of BIRC3 on tumor initiation." (PMID 35008722, 2021). "Shall BIRC3 downregulation in the tumor cells regarded as a positive fact?" (PMID 33413657, 2021). "BIRC3 is a mediator of survival by allowing tumor cells to adapt to hypoxia." (PMID 34488754, 2021). "It becomes of primary importance to define whether BIRC3 should be regarded as a proto-oncogene or, on the contrary, a tumor suppressor." (PMID 33413657, 2021). "Thus, at variance with BIRC3, survivin is considered as a pro-oncogenic protein and is commonly targeted to impair tumor cell proliferation." (PMID 33413657, 2021). "In support of this hypothesis, we present novel evidence that BIRC3 regulates stemness reprogramming, tumor initiation and tumor progression in GBM." (PMID 35008722, 2021). "Apart from that, MCPIP1 is recognized as a tumor suppressor due to its induction of apoptosis of tumor cells, for instance by selectively enhancing mRNA decay of antiapoptotic gene transcripts, including Bcl2L1, Bcl2A1, RelB, Birc3, and Bcl3." (PMID 31651935, 2019). "In complementary work, a tumor cell line that was selected for resistance to immunotherapy upregulated AKT compared with sensitive wild-type cells, and this was associated with increased levels of BIRC2 and BIRC3, BCL-2 and BCL-XL." (PMID 29163772, 2017). "In this study, we silenced E6/E7 in Caski and Ms751 cell and the whole-genome microarray analysis showed that many tumor microenvironment associated genes were down-regulated, such as NCR3, a gene associated with immune response, and BIRC3, a gene related to regulation of inflammatory response." (PMID 28303973, 2017). "Adjacent tumour suppressor pairs (e.g., CDKN2A/CDKN2B, BIRC2/BIRC3, HELQ/FAM175A...) may be especially rewarding targets for homozygous deletion in some cases, as two mutation events can abolish all tumour suppressor activity." (PMID 29089486, 2017). "In 7/8 paired samples, we showed an increase in the number of tumor cells expressing BIRC3 in the HGG tumor compared to the matched LGG (one paired sample showed an increase in BIRC3 expression in the HGG relative to the low-grade precursor but the difference was not statistically significant)." (PMID 27074575, 2017). "Importantly, the overexpression of XIAP independently is insufficient to stabilize endogenous BIRC3 implying that increased expression of BIRC3 must also occur to facilitate tumor growth and progression." (PMID 27074575, 2017). "Moreover, in human GBM xenografts robust BIRC3 expression was noted within hypoxic regions of the tumor." (PMID 28839258, 2017). "Elevated levels of BIRC3 have been shown by others to promote tumor cell survival, and the down-regulation of BIRC3 in RIIβ cells may indicate the release of a block to apoptosis which may account for, in part, for the decreased cell number in this cell type." (PMID 18822129, 2008). "Overexpression of MSL1 significantly increased BIRC3, an anti-apoptotic factor, and HLA-A, a class I HLA molecule associated with antigen presentation, suggesting that MSL1 modulates CD274-dependent downstream signaling, potentially affecting apoptosis and the tumor microenvironment." (PMID 41409271, 2025). "Furthermore, tumours in the altered BIRC3 group exhibited more spindle-shaped cells." (PMID 40997749, 2025). "Taken together, BIRC3 may promote necroptosis and regulate the expression of immune checkpoints through various biological mechanisms, thereby contributing to the establishment of an immunosuppressive tumour microenvironment." (PMID 38130918, 2023). "Additionally, studies have revealed the involvement of ERS and BIRC3 in tumor regulation." (PMID 38274787, 2023).